UBE3A (ubiquitin protein ligase E3A)
Diseases named in the same sentence as UBE3A in open-access papers (continued):
Sharing a sentence is not in itself a finding about the gene and the disease.
fragile X syndrome (11 papers, 2016 to 2024). A genetic syndrome caused by mutations in the FMR1 gene which is responsible for the expression of the fragile X mental retardation 1 protein. "To further investigate potential effects of UBE3A overexpression on cognitive function, we compared the performance of WT and Ube3a+2 mice on a task that was previously used to demonstrate enhanced operant extinction in both Angelman and fragile X syndrome model mice." (PMID 36134658, 2022).
Rett syndrome (10 papers, 2010 to 2025). A severe neurodevelopmental disorder affecting the central nervous system. "Decrease expression of UBE3A has also been observed in Rett syndrome patients." (PMID 28904337, 2017).
B-cell lymphoma (9 papers, 2012 to 2025). "Furthermore, UBE3A haploinsufficiency in an MYC-driven B-cell lymphomagenesis model increased PML levels, induced cellular senescence, and suppressed tumor progression, which is consistent with elevated levels of UBE3A and decreased levels of PML in primary B-cell lymphoma samples." (PMID 40002221, 2025).
Seizure (8 papers, 2021 to 2024). A seizure is an intermittent abnormality of nervous system physiology characterized by a transient occurrence of signs and/or symptoms due to abnormal excessive or synchronous neuronal activity in the brain. "Seizure susceptibility has been reported in Ube3a-del mice with a variety of seizure induction methods." (PMID 33549123, 2021).
Burkitt lymphoma (6 papers, 2012 to 2022). A rare form of malignant mature B-cell non-Hodgkin lymphoma. "In addition, UBE3A is hyperactivated in Epstein-Barr virus-associated Burkitt’s lymphoma and is involved in degrading the tumor repressor promyelocytic leukemia protein (PML)." (PMID 35368029, 2022). "Hemizygous disruption of the Ube3a gene can attenuate murine B-cell lymphomagenesis driven by the Eμ (immunoglobulin enhancer)-Myc transgene with concomitant upregulation of PML, recapitulating the oncogenic role of E6AP in Burkitt’s lymphoma." (PMID 32751183, 2020).
hepatoma (5 papers, 2022 to 2024). "ANXA2 acted an as an oncogene in hepatocellular carcinoma progression, which was modified by SIRT6/UBE3A." (PMID 35977942, 2022). "However, the roles of UBE3A in HCV- and HIV-1-triggered hepatocellular carcinoma and AIDS, respectively, are as yet unknown, and thus treatment of these diseases is still at its incipient stage." (PMID 37541588, 2023).
lung carcinoma (5 papers, 2017 to 2023). "E6AP/UBE3A is a multifaceted ubiquitin ligase that controls various signaling pathways implicated in neurological diseases and various cancers; however, its role in lung cancer is incompletely understood." (PMID 37454373, 2023).
non-small cell lung carcinoma (5 papers, 2019 to 2022). A group of at least three distinct histological types of lung cancer, including non-small cell squamous cell carcinoma, adenocarcinoma, and large cell carcinoma. "In approximately 20% of non-small cell lung cancer UBE3A levels are decreased, resulting in lower levels of the cyclin-dependent kinase (CDK) inhibitor p16INK4A and a reduction in overall survival." (PMID 33670160, 2021). "UBE3A has been shown to indirectly regulate p16 expression in non-small cell lung cancer." (PMID 32455880, 2020).
Parkinson disease (5 papers, 2012 to 2025). A progressive degenerative disorder of the central nervous system characterized by loss of dopamine producing neurons in the substantia nigra and the presence of Lewy bodies in the substantia nigra and locus coeruleus. "Investigating the UBE3A and the Parkin (Parkinson’s disease gene) simultaneously would benefit both diseases." (PMID 40076922, 2025). "Strikingly, growing evidence supporting aberrant UBE3A activity would contribute to the manifestations of an array of additional neurological disorders including schizophrenia, Huntington’s, Parkinson’s, and Alzheimer’s diseases, making UBE3A a protein of high research and clinical interest." (PMID 40076922, 2025). "Emerging evidence suggests that abnormal UBE3A activity may also contribute to the development of various brain disorders, including schizophrenia, Huntington’s disease, Parkinson’s disease, and Alzheimer’s disease, making UBE3A a protein of significant interest." (PMID 40076922, 2025).
schizophrenia (5 papers, 2022 to 2025). A major psychotic disorder characterized by abnormalities in the perception or expression of reality. "However, these phenotypes were similar to individuals with a maternal microduplication encompassing only UBE3A who do not present with seizures and have a family history of neuropsychiatric disorders including schizophrenia." (PMID 40316779, 2025).
viral infection (5 papers, 2019 to 2026). "Recent reports also indicated that UBE3A plays an integral part in regulating viral diseases, such as hepatitis C virus (HCV) and human immunodeficiency virus type I (HIV-1), by destabilizing proteins encoded by viruses." (PMID 37541588, 2023). "As reviewed above, the UBE3A function is multifarious and critical in regulating of various human and viral diseases." (PMID 37541588, 2023). "Collectively, these reports indicate that UBE3A function is multifarious and imperative to regulating various human and viral diseases." (PMID 37541588, 2023). "•UBE3A decays key viral proteins in the virus-infected cells and, thereby, impacts on the infected virus life cycle followed by the viral diseases." (PMID 37541588, 2023). "Therefore, this review is focused on the role of UBE3A in human and viral diseases and detailed molecular processes of UBE3A's mediation of those diseases." (PMID 37541588, 2023). "Hence, these formulations and the collection of other studies described in the present review evince the many remarkable capacities of UBE3A impactful to viral infection, human disease, and the growing mechanistic comprehension enabling their ultimate treatments and prevention." (PMID 37541588, 2023). "We found that c-Fos expression was decreased in the PFC of Ube3a 2xTg brains, and this reduction was partially rescued by SARNP viral infection." (PMID 38316900, 2024).
Alzheimer disease (4 papers, 2019 to 2025). A progressive, neurodegenerative disease characterized by loss of function and death of nerve cells in several areas of the brain leading to loss of cognitive function such as memory and language. "Here, we show that Ube3A is reduced in an Alzheimer’s disease mouse model, Tg2576 mouse, which overexpresses human APP695 carrying the Swedish mutation, and accumulates Aβ in the brain." (PMID 30937395, 2019). "This study establishes a molecular pathway that maintains a synaptic function and suggests Ube3A as a potential therapeutic target for Alzheimer’s disease." (PMID 30937395, 2019). "Taken together, our results place Ube3A as a critical player in Alzheimer’s disease pathogenesis, and as a potential therapeutic target." (PMID 30937395, 2019). "In Alzheimer’s disease, amyloid plaque is one of the typical pathological features that may be tightly regulated by UBE3A (discussed later)." (PMID 40076922, 2025). "This review discusses UBE3A expression in neurons and glial cells and highlights the newly identified properties of UBE3A, including its secretion and the involvement of UBE3A in neurodegenerative diseases such as Alzheimer’s disease (AD) and Huntington’s disease (HD)." (PMID 40076922, 2025). "Crucially, because there are already multiple treatments for AS that aim to upregulate UBE3A, these strategies could be repurposed or adapted to address UBE3A deficits in other neurocognitive disorders such as Alzheimer’s disease and related neurodegenerative conditions." (PMID 40076922, 2025). "However, previous studies have reported decreased UBE3A expression in Alzheimer's disease, although it is still uncertain whether this reduction is a cause or a consequence of amyloid accumulation." (PMID 40470739, 2025).
neuroblastoma (4 papers, 2015 to 2025). Neuroblastoma (NB) is the most common solid, extracranial childhood tumor. "UBE3A-silenced SH-SY5Y neuroblastoma cells represent an optimal in vitro cellular model for AS, already used and demonstrated." (PMID 41303513, 2025). "The proteasome receptor DDI1 has been identified both in Drosophila photoreceptor neurons and in human neuroblastoma cells in culture as a direct substrate of UBE3A." (PMID 31130875, 2019). "We investigated the autophagy process in wild-type (WT) and UBE3A-silenced (AS model; from now on UBE3A−) SH-SY5Y neuroblastoma cells." (PMID 41303513, 2025). "We recently discovered that Ube3a ubiquitinates endogenous Rngo in flies, and also its human homolog DDI1 when transfected in S5-SYHY neuroblastoma cells." (PMID 31130875, 2019). "However, basal levels of ERK activation remained unaltered following UBE3A depletion in both breast epithelial-derived MCF10A cells and neuroblastoma SH-SY5Y cells." (PMID 25815718, 2015).
Obesity (4 papers, 2013 to 2024). Accumulation of substantial excess body fat. "From earlier studies, we know that overweight and obesity is more prevalent in children with AS compared to their neurotypical peers and that reinstatement of UBE3A reverses overweight in an AS mouse model." (PMID 38429713, 2024).
pancreatic cancer (4 papers, 2019 to 2026). "Ubiquitin protein ligase E3A (UBE3A) is associated with various tumors; however, its potential role in pancreatic cancer warrants further investigation." (PMID 41748542, 2026). "Functional studies have demonstrated that UBE3A inhibits cellular senescence in pancreatic cancer cells, thereby promoting tumor proliferation and metastasis." (PMID 41748542, 2026). "Our results showed that UBE3A was significantly upregulated in pancreatic cancer tissues and correlated with poor patient outcomes." (PMID 41748542, 2026). "UBE3A interacts with mH2A1 through its N-terminal domain, leading to K48-linked polyubiquitination at the K167 residue, which accelerates mH2A1 degradation and upregulates TERT, enhancing the anti-senescence capacity of pancreatic cancer cells." (PMID 41748542, 2026). "The UBE3A/mH2A1/TERT axis enhances the anti-senescence capacity of pancreatic cancer cells and drives malignant progression, suggesting that UBE3A may serve as a novel therapeutic target for pancreatic cancer." (PMID 41748542, 2026).
cardiac hypertrophy (3 papers, 2020 to 2024). "The Ube3a gene has recently emerged as a new biomarker of hypertrophy, having previously been shown to be associated with myocardial hypertrophy." (PMID 38047311, 2024). "Conversely, UBE3A knockdown by siRNAs exacerbated isoproterenol-induced cardiac hypertrophy by activating the TLR4/MMP-9 pathway." (PMID 38515760, 2024). "UBE3A is one of the important members of UPS; Ube3a mutant mice had deficits in Ca2+/calmodulin-dependent kinase II (CaMKII), while CaMKII played a vital role in cardiac hypertrophy." (PMID 32595699, 2020). "UBE3A is vital for alleviating cardiac hypertrophy via the UBE3A/TLR4/MMP-9 pathway." (PMID 38515760, 2024).
cervical (3 papers, 2018 to 2020). "Deregulation of the HECT-type ubiquitin ligase E6AP (UBE3A) is implicated in human papilloma virus-induced cervical tumorigenesis and several neurodevelopmental disorders." (PMID 30737286, 2019). "The HECT‐type ubiquitin ligase E6AP (UBE3A) is critically involved in several neurodevelopmental disorders and human papilloma virus‐induced cervical tumorigenesis; the structural mechanisms underlying the activity of this crucial ligase, however, are incompletely understood." (PMID 31994269, 2020).
liver cancer (3 papers, 2020 to 2023). An epithelial or non-epithelial malignant neoplasm that arises from the liver. "NS5B traps pRb in the cytoplasm and recruits UBE3A to NS5B and pRb complex for UBE3A-mediated degradation of pRb, which promotes hepatocellular proliferation for the development of liver cancer." (PMID 37541588, 2023). "For example, UBE3A degrades ZNF185 to activate the NOTCH pathway; UBE3A targets SIRT6 in an ANXA2-dependent manner, leading to tumorigenesis of liver cancer." (PMID 37385985, 2023).
renal carcinoma (3 papers, 2021 to 2023). A carcinoma arising from the epithelium of the renal parenchyma or the renal pelvis. "Knockdown of UBE3A by specific shRNAs decreased cell proliferation in both 786-O and ACHN cells, but overexpression of UBE3A through ectopic Flag-UBE3A transfection upregulated renal cancer cell growth ability." (PMID 35368029, 2022). "Here, we showed that genetically repressing UBE3A expression decreased the cell proliferation activity of renal cancer cells." (PMID 35368029, 2022). "In summary, we demonstrated that UBE3A functions as a newly found E3 ligase of PBRM1 in renal cancer cells." (PMID 35368029, 2022). "In summary, we not only revealed a novel RBPJ/DAPK3/UBE3A/PBRM1/p21 signaling axis but also identified a combination strategy for overcoming the resistance of renal cancer cells to CDK4/6 inhibitors." (PMID 35368029, 2022). "An in vitro study in which MTS assay and colony formation analysis were performed also indicated that knockdown of UBE3A sensitized renal cancer cells to palbociclib." (PMID 35368029, 2022). "In summary, our results demonstrate that the RBPJ/DAPK3/UBE3A/PBRM1/p21 signaling pathway regulated the sensitivity of renal cancer cells to CDK4/6 inhibitors." (PMID 35368029, 2022). "Meanwhile, we also showed that the protein level of UBE3A was negatively correlated with the PBRM1 protein level in the renal cancer patient specimens." (PMID 35368029, 2022). "Moreover, the RBPJ/DAPK3/UBE3A/PBRM1/p21 axis induced increased sensitivity of renal cancer cells to CDK4/6 inhibitors." (PMID 37385985, 2023). "Since PKA was reported to phosphorylate UBE3A and inhibit its E3 ligase activity., we were curious about whether other proteins affected the function of UBE3A in renal cancer." (PMID 35368029, 2022). "The subsequent coimmunoprecipitation experiment verified that PBRM1 and UBE3A could bind to each other in 293T and renal cancer cell lines (786-O and ACHN cells)." (PMID 35368029, 2022). "Finally, we demonstrated that the RBPJ/DAPK3/UBE3A/PBRM1/p21 axis contributed to the sensitivity of renal cancer cells to CDK4/6 inhibitors." (PMID 35368029, 2022). "Therefore, we not only revealed a novel RBPJ/DAPK3/UBE3A/PBRM1/p21 axis but also identified a combination strategy for overcoming the resistance of renal cancer cells to CDK4/6 inhibitors." (PMID 35368029, 2022). "We found that the knockdown of UBE3A increased the PBRM1 protein level in renal cancer cells." (PMID 35368029, 2022). "Thus, our results indicate that PBRM1 is a bonafide substrate of UBE3A and is involved in proteasomal degradation in renal cancer cells." (PMID 35368029, 2022). "In addition, we checked the clinical relevance of PBRM1 and UBE3A in a tissue microarray of patients with renal cancer." (PMID 35368029, 2022). "Moreover, our data suggest that the RBPJ/DAPK3/UBE3A/PBRM1/p21 axis modulated the sensitivity of renal cancer cells to CDK4/6 inhibitors." (PMID 35368029, 2022). "Then, we checked whether UBE3A modulated the sensitivity of cell-cycle-related antitumor small molecules, mainly cyclin-dependent kinases, in renal cancer cells." (PMID 35368029, 2022). "Moreover, we found that RRM2 interacted with and stabilized ANXA1 in renal cancer cells by competing with UBE3A." (PMID 34319001, 2021). "Together, these findings demonstrate that UBE3A interacts with PBRM1 and UBE3A silencing increases the PBRM1 protein levels in renal cancer cells." (PMID 35368029, 2022). "Therefore, we hypothesized that UBE3A might promote PBRM1 degradation in renal cancer cells." (PMID 35368029, 2022). "In this study, we performed unbiased mass spectrometry of PBRM1 and identified ubiquitin-protein ligase E3A (UBE3A), an extensively studied E3 ligase that can bind with PBRM1 and regulate the stability of PBRM1 in renal cancer cells." (PMID 35368029, 2022).
renal carcinoma (continued). "In this study, we performed unbiased mass spectrometry of PBRM1 and identified ubiquitin-protein ligase E3A (UBE3A), a well-known E3 ligase, that can bind with PBRM1 and regulate the stability of PBRM1 in renal cancer cells." (PMID 35368029, 2022). "Together, these data suggest that DAPK3 is a binding partner of UBE3A and critical for PBRM1 degradation in renal cancer cells." (PMID 35368029, 2022). "At first, reciprocal coimmunoprecipitation assays confirmed the interaction between UBE3A and DAPK3 in 293T and renal cancer cell lines (786-O and ACHN cells)." (PMID 35368029, 2022). "In conclusion, our results suggest that RRM2 overexpression in renal cancer cells plays a key role in sunitinib resistance in patients with RCC and that RRM2 competes with UBE3A to bind to the C‐terminus of ANXA1, preventing ANXA1 degradation." (PMID 34319001, 2021). "We found that there were higher expression levels of UBE3A in renal cancer tissues than in adjacent nontumor tissues." (PMID 35368029, 2022). "To explore whether DAPK3 destabilized PBRM1 through UBE3A in renal cancer cells, we performed knockdown of DAPK3 and UBE3A alone or in combination in 786-O and ACHN cells." (PMID 35368029, 2022). "Therefore, our results indicate that DAPK3 competes with PKA to bind with UBE3A and enhances the degradation of PBRM1 in renal cancer cells." (PMID 35368029, 2022). "However, overexpression of DAPK3 strengthened the degradation of PRBM1 induced by UBE3A WT or T508A mutant, which was independent of the kinase activity of DAPK3 in renal cancer cells." (PMID 35368029, 2022).
channelopathy (2 papers, 2021 to 2023). Channelopathies are a group of diseases caused by the dysfunction of ion channel subunits or their interacting proteins. "When characterizing the functional properties of cortical organoids derived from genome-edited UBE3A knockout human embryonic stem cells (hESCs) and AS-hiPSCs, an evolutionarily conserved channelopathy was identified that contributes to network dysfunction and hyperactivity in AS." (PMID 37569905, 2023).
colon cancer (2 papers, 2011 to 2025). "In the evaluated 20 colon cancer cell lines, all but one (UBE3A) gene promoters were hypermethylated with frequencies ranging from 20% (LEF1 and MEF2C) to 100% (CNRIP1)." (PMID 21777459, 2011).
dementia (2 papers, 2018 to 2024). Loss of intellectual abilities interfering with an individual's social and occupational functions.
Dup15q (2 papers, 2018 to 2019). "UBE3A is an E3 ubiquitin ligase that targets proteins for degradation and trafficking, so finding UBE3A substrates and interacting partners is critical to understanding Dup15q ASD." (PMID 30787400, 2019).